MICA (MHC class I polypeptide-related sequence A)
Diseases named in the same sentence as MICA in open-access papers (continued):
Sharing a sentence is not in itself a finding about the gene and the disease.
tumor (continued). "Although chemotherapeutic or genotoxic stresses have been implicated in the upregulation of all of the molecules identified as being upregulated by GEM, this investigation may be the first time that a single agent has been shown to increase CD95, TRAILR2, MICA/B and ULBP2/5/6 on tumour cells." (PMID 30733494, 2019). "On the other hand, tumor-directed recombinant ligands that engage NKG2D may also enhance tumor cell targeting, as recently documented against malignant B cells for bispecifics composed of CD20-binding and NKG2D ligand (MICA or ULBP2) domains." (PMID 29740448, 2018). "In conclusion, in this paper we have described the detection of the non-abundant tumour-derived antigen MICA in exosomes using two immunodetection-based methods and we describe the different parameters that require careful optimization for the implementation of new exosome markers." (PMID 29720199, 2018). "However, the results were consistent with MICA mRNA level in HCC and non-tumour tissues." (PMID 28928439, 2017). "In addition, tumor cells can also shed alarm proteins, such as the major histocompatibility complex (MHC) class I polypeptide-related sequence A (MICA) or B7-H6, thereby dampening NKG2D-mediated activation of T cells and NK cells or NKp30-mediated activation of NK cells." (PMID 27598210, 2016). "As HSF1 has been described to regulate the transcription of the NK cell ligands MICA and MICB, we investigated whether treatment of tumor cells with NZ28 and/or NVP-AUY922 alters the cell surface density [mean fluorescence intensity (MFI)] of the NK cell ligands MICA and MICB on tumor cells." (PMID 25854583, 2015). "However, MICA binds in mutually exclusive manner to NKG2D and TCR, suggesting that the two receptors might be sequentially engaged following recognition of target tumor cells." (PMID 25538706, 2014). "Thus, serum MICA/B molecules released from tumor cells act as a negative force to counteract the effect of membrane-bound MICA/B in immune surveillance and sensitization for immune cell killing." (PMID 21605422, 2011). "Different activating receptors confer to NK cells the capacity to kill virus-infected or tumor cells; one of these receptors is represented by NKG2D, which can recognize different ligands including MICA molecules; thus, NKG2D could have a significant role in anti-tumor immune response." (PMID 18208618, 2008). "NK and cytotoxic T cells play an important role in the elimination of virus-infected and tumor cells through NKG2D activating receptors, which can promote the lysis of target cells by binding to the major histocompatibility complex class I-related chain A (MICA) proteins." (PMID 18208618, 2008). "Therefore, targeting both forms of MICA/B (soluble or cell surface-expressed) with Ab-based strategies emerges as a “two-in-one” strategy that can boost ADCC (immunosurveillance) and that can interfere with the immunosuppressive effect of sMICA/B (tumor immune escape)." (PMID 34394116, 2021). "Moreover, the MICA/B α3 domain–specific mAb could also be engineered into NK cells for adoptive cell transfer to boost efficient tumor cell targeting, with no toxic off-target cell killing." (PMID 32283827, 2020). "We found that ectopic MICA and MICB could induce a strong proliferative response on those cells, suggesting the possibility of an autoregulatory mechanism by which MICA and MICB secreted by the tumor cells are recognized by their own NKG2D receptor to contribute to tumor cell proliferation." (PMID 21477352, 2011). "These antibodies not only do not hinder the binding of MICA/B to NKG2D but also can activate NK cells through their Fc fragments and enable NK cells to secrete anti-tumor cytokines such as IFN-γ." (PMID 40563539, 2025). "MICA and MICB are not expressed or expressed at a low level in normal tissue cells but are highly expressed on the surface of various tumor cells." (PMID 40563539, 2025).
tumor (continued). "Unlike stress-induced activation mechanisms such as MICA/B or ULBPs, PLAC1 offers an additional interaction with NK cells, potentially enhancing tumor recognition and killing." (PMID 40607388, 2025). "Unlike their healthy counterparts, transformed tumor cells are often found to express ligands like major histocompatibility complex (MHC) class 1 chain–related proteins A and B (MICA and MICB)." (PMID 38239881, 2023). "NKG2D ligands (class I MHC-like proteins, including MHC class I-related chain A (MICA) and MICB) are mainly present in tumor cells, and not normal cells." (PMID 38033491, 2023). "The significant positive correlation of MICA expression and NK cells & CD8+T cell infiltration in HCC tumor and non-cancerous tissue was confirmed by IHC staining." (PMID 36765808, 2023). "Notably, among the five major NKG2DL, MICB was the main NKG2DL regulated by MYC in H2227 cells, while MICA was the main one regulated by MYC in H446 cells, indicating that the regulatory pathways of the same NKG2DL may be different in distinct tumor cells, which required to be further studied." (PMID 35158730, 2022). "The expression of NK ligands (CD155, CD112, MICA/B, and ULBP1) on single tumor cells in the s.c model did not vary among the control, NK-IVlow, Bev plus Irihigh, and NK-IVlow combined with Bev plus Irihigh groups." (PMID 36703992, 2022). "NKG2D ligands include MICA, MICB and ULBP1-6, which are expressed on the surface of most tumor cells but almost absent from the surface of normal cells." (PMID 35965586, 2022). "Accordingly, preformed anti-MICA immune complexes containing wild-type Fc effector function induced IFN-γ and TNF-α secretion by NK cells in the absence of tumor cells." (PMID 31387641, 2019). "An important NKG2D ligand is the MHC class I chain A and B (MICA and MICB) and UL16-binding proteins (ULBPs), which are expressed at low levels on the non-malignant cell types while primary tumor cells and tumor cell lines frequently express NKG2D ligands." (PMID 26439264, 2015). "K562 tumor cells express ligands for receptors promoting natural cytotoxicity (Nectin-2/PVR for DNAM-1; MICA/B/UBLP1 for NKG2D), but do not express the 2B4 ligand CD48 or classical HLA-A, B, C, and non-classical HLA-E." (PMID 23508354, 2013). "Other non-genotoxic anticancer drugs can also increase MICA/B and other NKG2D ligand expression in various tumor cell lines and in patients." (PMID 21605422, 2011). "It is not known if the secretion of MICA and MICB by the tumor cells has any effect on the cancer cells themselves." (PMID 21477352, 2011). "IHC staining with an anti-MICA/B mAb (SR99) revealed the strong dark brown signal of MICA/B expression present in the tumor cells but not in normal ductal cells nor in a cyst adenoma." (PMID 21605422, 2011). "Here we show that MICA and MICB exhibit differential expression patterns among HPV-infected (SiHa and HeLa) and non-infected cell lines (C33-A, a tumor cell line, and HaCaT, an immortalized keratinocyte cell line)." (PMID 21631944, 2011). "In tumour cells that evade the NK cells, galectin-3 binds to poly-N-acetyllactosamine in the NKG2D-binding site of MICA, thereby preventing the interaction of MICA with NK2GD, and the apoptotic mechanisms are not triggered to promote longer circulation of the tumour cells." (PMID 37444377, 2023). "It was observed that the exosome-mediated down-modulation of NKG2D was inhibited by anti-MICA, but not isotype- control Ab, confirming that reduced NKG2D surface expression occurs with tumor but not with non-tumor exosomes, and is at least in part due to exosomal MICA expression." (PMID 35031075, 2022). "With multiple advantages of easy ex vivo expansion, minor GVHD, natural tumor trafficking and non-MHC restricted, CIK cell-based therapy may serve as a potent combination partner with MICA antibody-mediated immunotherapy." (PMID 32645836, 2020).
tumor (continued). "Our data also indicate that in contrast to other NKG2DL such as MICA, MICB, and ULBP1–3, which are frequently expressed on a broad variety of human tumor cell lines, ULBP4 may be not or only sparsely expressed on the surface of human tumor cell lines." (PMID 29651291, 2018). "Similarly, with respect to a possible heterogeneity of MICA and MICB expression within the tumor, our analyses revealed that both the expression as well as the lack of it was homogenous throughout the tumor." (PMID 26902929, 2016). "Thus, to confirm the lack of MICA and MICB expression in a completely independent set of samples, we analyzed 50 additional MCC tumor samples of 34 patients for their MICA and MICB expression by IHC in conventional tumor sections." (PMID 26902929, 2016). "We hypothesized that using a protein-derived neoepitope primarily upregulated in transformed cells experiencing stress and contributing to tumor escape mechanisms will be favorable for the efficacy of CAR therapy, since surface expression of MICA/B is typically low or absent in healthy tissues." (PMID 41050431, 2025). "Nonetheless, the lack of conservation of human ULBP6 and MICA/B in mice and the species differences in FcγR expression and affinities to hIgG1 limit our ability to evaluate the role of ULBP6 and 23ME-01473-mediated NKG2D and FcγRIIIa activation on tumor growth in the MC38 model." (PMID 40116579, 2025). "Notably, protein degradation inhibitors failed to rescue the expression of MICA, MICB, and ULBP3, indicating that the reduced protein levels of MICA, MICB, and ULBP3 in the infected tumor cells were due to the impaired translation of these ligands, and not due to increased protein degradation." (PMID 37753084, 2023). "Although NKG2D ligands, including MICA and MICB, are up-regulated during malignant transformation in response to oncogenic activation, their expression can be down-regulated both transcriptionally and non-transcriptionally at the level of tumor cells to escape antitumor the immune response." (PMID 28423623, 2017).
cancer (264 papers, 2006 to 2026). A tumor composed of atypical neoplastic, often pleomorphic cells that invade other tissues. "MICA shedding by cancer cells causes effective escape from NKG2D recognition and allows the development of cancers." (PMID 40145650, 2025). "Cell surface release of MICA in a soluble form (sMICA) has been implicated in cancer cell escape from NK cell immune surveillance, and rs3763288 forms a quantitative trait locus for blood sMICA levels." (PMID 40712021, 2025). "These MICA/ NKG2D associated miRNAs provide insight into the development of novel therapeutic cancer targeting medicines." (PMID 37784183, 2023). "The second marker used, MICA, has been associated with cancer progression in many types of solid and haematological tumours." (PMID 35135541, 2022). "This is supported by other studies, which indicate that high-cell surface MICA/B expression in cancers of the digestive tract was associated with increased patient survival." (PMID 33868281, 2021). "MICA gene is highly polymorphic, thus originating alleles that encode protein variants with a controversial role in cancer." (PMID 33868281, 2021). "Here, we observed that the presence of MICA*009/049 (MICA*A6) allele increases the susceptibility of developing GC, thus constituting a genetic risk factor for this type of cancer." (PMID 33868281, 2021). "MICA polymorphic variants have been associated to several autoimmune and inflammatory diseases, as well as cancer." (PMID 33868281, 2021). "designed antibodies targeting the MICA α3 domain and found that these antibodies prevented human cancer cells from loss of cell surface MICA and MICB (NKG2D ligands)." (PMID 35095898, 2021). "Although the associations of MICA polymorphisms with genetic predisposition to different cancer types have been investigated in candidate gene-based studies, these previous studies predominantly focused on polymorphisms within the TM." (PMID 32528529, 2020). "This variant was related to the expression of MICA, a stress-induced gene expressed by cancer cells, function as ligands for NKG2D receptors." (PMID 32010612, 2019). "Consistent with our reports, several investigators have demonstrated that the MICA A5.1 allele appears to modulate cancer susceptibility in both candidate gene and genome-wide association studies (GWAS)." (PMID 31166958, 2019). "Different mechanisms of transcriptional repression have been described only for MICA; they are caused by cell type-specific proteins, the expression and/or function of which is often critical for the survival and proliferation of cancer cells." (PMID 29662484, 2018). "The expression levels of MICA/B on cancer cell surface were significantly associated with OS in patients with digestive system cancer." (PMID 29221214, 2017). "No significant statistical difference was observed for the association between MICA/B expression and survival in all types of cancer." (PMID 29221214, 2017). "In line, another study shows that doxycycline enhances susceptibility of cancer cells to CIK cells by increasing MICA/B membrane expression." (PMID 28701757, 2017). "Conversely, a high MICA/B expression was associated with a favorable outcome in cancers of the digestive system, supporting the notion that MICA/B is a critical ligand in immune cytotoxicity." (PMID 29221214, 2017). "Immune effector molecules MICA/B not only reflect a distinct underlying biology of the tumor, but they are also involved in innate immune activation and cancer immune tolerance." (PMID 29221214, 2017). "Polymorphisms of MICA have been investigated for their role in infections, autoimmune diseases, and cancer." (PMID 28018354, 2016). "Elevated levels of soluble MICA have been detected in the sera of patients with various types of cancer, and the levels of soluble MICA can be used as a diagnostic marker for cancer progression." (PMID 23209462, 2012).
cancer (continued). "Here, we studied miRNAs with potential novel binding sites to SNPs located in MICA 3′UTR by in silico analysis; we also discuss their possible implications in the regulation of MICA expression in cancer, emphasizing the relevance of MICA alleles in this post-transcriptional modulation." (PMID 38146340, 2023). "Interestingly, MICA/B is also cleaved by metalloproteinases to form a soluble form, and the determination of soluble MICA levels can be used as an immunological diagnostic marker in patients with epithelial malignant tumors." (PMID 37426678, 2023). "Additionally, increased levels of soluble MICA are associated with poor prognosis and disease progression for various cancer types." (PMID 34926577, 2021). "Cleavage inhibition was not unique to the C1R cell line, as multiple cell lines derived from different cancers and harboring different MICA alleles were also sensitive to α3 domain specific antibodies, including HCC1534, MEL-JUSO and SK-MEL cells (data not shown)." (PMID 31387641, 2019). "The results of these disease association studies do not allow for a simple unifying interpretation, such as the high-affinity MICA-129Met variant being associated with an activation of the immune system resulting in a lower risk of infections and cancer but higher risk of autoimmunity." (PMID 28018354, 2016). "Furthermore, polymorphisms in the major histocompatibility complex class I-related chain A (MICA), which are critical for eliminating malignant tumors, have been associated with carcinogenesis in adolescents and YA with OCSCC, suggesting their potential as cancer markers in this age group." (PMID 39421447, 2024). "We then compared, within the same cancer cells, the synaptic distribution of MICA/B to that of HLA-A, -B, and -C." (PMID 40763024, 2025). "This resulted in increased expression of membrane-bound MICA (MHC Class I polypeptide-related sequence A), a cancer cell ligand that triggers natural killer cell attack, and it is an ADAM9 substrate." (PMID 40427200, 2025). "Paradoxically, cancer cells employ multiple immune evasion mechanisms, including proteolytic shedding of MICA by ADAM metallopeptidases." (PMID 40726981, 2025). "NKG2D is found on both NK cells and T cells and binds ligands typically expressed on stressed and transformed cells, e.g. the proteins MICA/B (MHC class I polypeptide–related sequence A/B) which can be upregulated on the surface of cancer cells." (PMID 40791601, 2025). "Despite these clinical findings, the mechanism of MICA release by human cancer cells is not completely understood." (PMID 39837817, 2025). "MICA undergoes post-translational modifications that regulate their expression as they are called membrane-bound MICA (mMICA) at the cancer cell surface." (PMID 40726981, 2025). "Using confocal microscopy, we selected conjugates formed with either primary NK cells or NK-92MI cells that exhibited strong synaptic F-actin polarization within the cancer cell, along with detectable surface levels of MICA/B." (PMID 40763024, 2025). "In contrast, other NKG2DLs, such as MICA/B, exhibited high expression across most of the evaluated cancers." (PMID 40116579, 2025). "In adult cancer patients, plasma levels of soluble MICA and ULBP2 proteins are elevated and have been shown to inhibit NK function." (PMID 39310750, 2024). "When activating receptors, such as DNAM-1, NKG2D (Rae1δ in the murine system), and NKp46, bind to their ligands CD155 and MICA/B on cancer cells, it increases NK cell cytokine production, and further promotes cancer cell apoptosis." (PMID 38893071, 2024). "In numerous types of cancers, the expression of immune sensors, such as MICA, FAS, MHC-I, CD155, ULBP 2/5/6, are down-regulated, which causes disorders in the recognition of cancer cells by immune cells." (PMID 38589867, 2024). "HDAC inhibitors also potently increase MICA/B expression by several cancer types, thereby promoting NK‐cell‐driven immunity." (PMID 38882209, 2024).